ACE (angiotensin I converting enzyme)
Diseases named in the same sentence as ACE in open-access papers (continued):
Sharing a sentence is not in itself a finding about the gene and the disease.
cardiac hypertrophy (83 papers, 2010 to 2026). "Conversely, the D allele (deletion variant) and DD genotype are associated with higher ACE activity and have been linked to greater cardiac hypertrophy (or enlargement of the heart muscle) and power-oriented activities." (PMID 39684752, 2024). "An insertion/deletion variant in the ACE, which is associated with variation in the plasma levels of ACE, modestly modifies cardiac hypertrophy and the risk of SCD in HCM." (PMID 37629714, 2023). "Increased production of Ang-2, facilitated by the ACE enzyme and the D allele, supports blood flow redistribution during intense exercise but, if unregulated, can also promote cardiac hypertrophy and maladaptive remodeling through pathways involving angiotensin II." (PMID 39684752, 2024). "Reduction of elevated blood pressure by ACE inhibitors including trandolapril was reported to decrease arterial stiffness and pulse wave velocity, which was associated with a significant regression of cardiac hypertrophy." (PMID 34566652, 2021). "Isorhamnetin and its derivatives demonstrate ROS-scavenging capacity while their antihypertensive effects are associated with ACE inhibition and blockade of the PI3K/AKT signaling pathway, preventing cardiac hypertrophy and fibrosis." (PMID 41515425, 2025). "They found that ARNI distinctly improved LV size and hypertrophy compared with ACE inhibitors/ARBs in HFrEF patients, even after short-term follow-up." (PMID 37733084, 2024). "Current treatment options for cardiac hypertrophy primarily involve the use of β‐blockers, calcium antagonists, and angiotensin‐converting enzyme (ACE) inhibitors via enhancing cardiac systolic and diastolic function." (PMID 39351650, 2024). "A significant reduction in cardiac hypertrophy was observed in the Captopril group, where the mean value was 3.41 ± 0.06 g/kg, according to the ACE-inhibitor profile of this compound." (PMID 38398831, 2024). "miR-21 was alsoupregulated in a cardiac hypertrophy model induced by uremia, in which bothmiR-21 and miR-29 were downstream of angiotensin-converting enzyme (ACE) andangiotensin receptor 1a (ATR1)." (PMID 39076878, 2023). "Interference with BRG1 and FOXM1 or the chemical inhibition of FOXM1 can abrogate the cardiac-stress-induced shift from ACE2 to ACE and protect the heart from myocardial hypertrophy." (PMID 37238726, 2023). "The activity of angiotensin-converting enzyme (ACE), which converts angiotensin (Ang) I into Ang II, is elevated in cardiac hypertrophy and damaged hearts." (PMID 36769115, 2023). "Brahma-related gene-1 (BRG1) and FOXM1 acted together in pathologically stressed cardiac endothelial cells, triggering the conversion of ACE2 into ACE and angiotensin I into angiotensin II, respectively, leading to myocardial hypertrophy." (PMID 37238726, 2023). "A meta-analysis of clinical studies from 2010 to 2019 revealed that ARNI exerted reverse remodelling in terms of reduced LV size and hypertrophy compared with ACE inhibitors or AT1R blockers in patients with HF with a reduced LV ejection fraction." (PMID 36009391, 2022). "The role of ACE2, ACE and their peptides has been well recognized in different inflammatory conditions including acute pancreatitis, lung injury, pulmonary hypertension, cardiac hypertrophy, sepsis, and glomerulonephritis." (PMID 35281029, 2022). "One is the classical angiotensin-converting enzyme (ACE), angiotensin II, and angiotensin type I receptor pathway, which is associated with vasoconstriction, myocardial hypertrophy, and sodium/water retention." (PMID 35498011, 2022). "The antioxidants therapies are considered to have an advantage for the treatment of cardiac hypertrophy over ACE inhibitors or AT1R blockers." (PMID 36359731, 2022). "The combined use of amlodipine, a calcium-channel blocker, and benazepril, an ACE inhibitor, decrease arterial stiffness and ventricular hypertrophy." (PMID 34351937, 2021).
cardiac hypertrophy (continued). "In rats, age-related reductions of myocardial mitochondrial mass were successfully reversed and cardiac hypertrophy attenuated with the use of ACE-inhibitors during aging." (PMID 33499156, 2021). "It has repeatedly been shown that ACE inhibition and AngII receptor antagonism are effective treatments against blood pressure elevation and the progression of concomitant observed heart hypertrophy and remodeling in the Dahl rat." (PMID 34349662, 2021). "The AT1 blockers or angiotensin converting enzyme (ACE) inhibitors have been successfully used to reduce hypertrophy and cardiac fibrosis in this model." (PMID 29059221, 2017). "Glomerular hypertrophy is observed in oxonic acid-induced hyperuricemia and can be prevented by ACE inhibitor therapy in the rats." (PMID 28979210, 2017). "The ACE/NEP inhibitor reduced cardiac hypertrophy more than ARNI, possibly because the ACE/NEP inhibitor also had a greater effect on blood pressure compared with ARNI." (PMID 27837397, 2016). "It is reported that ACE inhibitors can reduce the synthesis of angiotensin II and attenuate such cardiac hypertrophy pathophysiological processes." (PMID 24204726, 2013). "Additionally, mRNA expression levels of ANP, ET-1, and ACE are established molecular markers of pathological cardiac hypertrophy." (PMID 40871685, 2025). "Furthermore, a meta-analysis study encompassing clinical studies related to the effect of ACE inhibitors in cardiac hypertrophy demonstrated that ACE drugs were better than β-blockers and diuretics in reducing the left ventricular mass index." (PMID 36769755, 2023). "RAAS-induced cardiac hypertrophy could occur through the classic RAAS pathway (ACE/AngII/AT1R) while being preventing by the new RAAS pathway (ACE2/Ang1–7/Mas1R and AT2R)." (PMID 36288152, 2022). "On the other hand, ACE inhibitors are more potent in preventing cardiac hypertrophy induced by ACF." (PMID 33608612, 2021). "Finally, Taurisolo® 20 mg/Kg/die induced also significant prevention of the cardiac hypertrophy developed by SHRs, for which the gold standard is represented by ACE-inhibitors like Captopril." (PMID 34063322, 2021). "Similarly, treatment of SHR dams with the ACE inhibitor captopril reduced heart hypertrophy, fibrosis, and vascular remodeling in the offspring." (PMID 35366262, 2021). "Like the reference drug (enalapril 10 mg/body mass/day), an ACE inhibitor, the methanolic extract inhibited plasmatic ACE activity, enhanced cardiac hypertrophy and normalized baroreflex sensibility, suggesting the efficiency of this extract as an anti-hypertensive." (PMID 31315213, 2019). "Additionally, ACE2 overexpression protects against ACE-mediated cardiac hypertrophy and cardiac fibrosis." (PMID 28091615, 2017). "The ACE inhibitor cilazapril also prevented cardiac hypertrophy in TG mice." (PMID 28771545, 2017). "However, a meta-analysis study that encompasses clinical studies directed to evaluate the role of ACE inhibitors in cardiac hypertrophy, demonstrated that ACE drugs were more potent than β-blockers and diuretics reducing left ventricular mass index." (PMID 27347925, 2016). "The observed left ventricle reduction in ACE activity (-43%) could be related to the observed improvement in hypertrophy and cardiac function." (PMID 26010093, 2015). "In this context, other indicators of superior adaptation to exercise resulting in better athletic performance (such as ventricular hypertrophy, VO2 max, and competition results) were mostly used to study the association between ACE I/D polymorphism and improved performance." (PMID 25586030, 2012). "Considering the role of the serotonin and angiotensin systems in cardiac hypertrophy, we hypothesized that DNA variants in the 5-HT2A, 5-HTT, AGT, ACE, and AT1R genes could influence the risk for LVH." (PMID 20594303, 2010).
cardiac hypertrophy (continued). "Apart from AT1R blockers, ACE inhibitors such as enalapril, ramipril, benazepril, zofenopril, lisinopril, fosinopril, perindopril, and imidapril which reduce the formation of Ang II, have been evidenced for their beneficial effects in attenuating pathological cardiac hypertrophy." (PMID 36359731, 2022). "While increased SBP and upregulated ACE-ANGII-AT1 axis may have contributed predominantly to nicotine-induced cardiac hypertrophy observed, recent in vitro studies have also suggested that nicotine may directly increase cardiomyocyte size through calcineurin/NFAT signaling and ROS production." (PMID 31920673, 2019). "In recent years, a pivotal role of ACE2, ACE and their peptides were recognized during the inflammatory process such as glomerulonephritis, pulmonary hypertension, sepsis, lung injury, acute pancreatitis and also cardiac hypertrophy, while also being a key part of the renin–angiotensin system." (PMID 28336767, 2017). "BRG1 and FOXM1 were activated to form transcriptional protein complexes at the ACE and ACE2 gene promoters, transcriptionally activating ACE and repressing ACE2, promoting angiotensin II production, and leading to myocardial hypertrophy and fibrosis." (PMID 37238726, 2023). "NEP antagonists alone and in combination with ACE (angiotensin converting enzyme) and ECE (endothelin converting enzyme) inhibitors were able to improve cardiac function, limit cardiac hypertrophy, and decrease systemic blood pressure." (PMID 33912600, 2021). "In the myocardium, ACE and ACE2 expression, as well as cardiac hypertrophy, are significantly higher in spontaneously hypertensive male mice compared to female mice." (PMID 32331343, 2020). "After orchiectomy, a significant decrease in ACE, ACE2 expression and cardiac hypertrophy was found and, consequently an increased cardiac performance was observed." (PMID 32331343, 2020). "(2005) obtained different results, showing that administration of SPI to rats with cardiac hypertrophy increases expression of ACE2 and decreases that of ACE." (PMID 31165585, 2019). "The EE and BF of U. wallichiana attenuated cardiac hypertrophy by decreasing SBP and HR and inhibiting plasma renin, ACE, Ang II and augmented plasma NO and cGMP concentration." (PMID 28066255, 2016). "On the other hand, our data on heart weights and dimensions in rats with HF suggest that AT1 receptor blockers do not prevent eccentric cardiac hypertrophy as effectively as ACE inhibitors." (PMID 33608612, 2021). "However, it was reported that when the pharmacological blockade of RAS by ACE inhibitor (ACEi) was employed in ACF TGR, the protective effect was dominantly mediated by attenuation of cardiac hypertrophy." (PMID 34440257, 2021). "ACE inhibitor enalapril at a dose that did not significantly lowered BP, attenuated cardiac hypertrophy while moderately improving cardiac function without reducing proteinuria and serum creatinine level." (PMID 25775254, 2015). "Other variants at the AGT, ACE, 5-HT2A and 5-HTT did not contribute to the risk of cardiac hypertrophy." (PMID 20594303, 2010). "Notably, EA was effective in reversing the expression patterns of ACE and AT1R and AT2R in SHR (P < 0.01, P < 0.001), which might mediate the inhibitory effects of EA on myocardial hypertension and hypertrophy." (PMID 28293268, 2017). "Although the exact mechanism by which the ACE I/D polymorphism affects cardiac adaptations is not fully understood, the renin-angiotensin system (RAS) and associated microRNAs are thought to play a central role by regulating expression throughout the molecular pathways of cardiac hypertrophy." (PMID 39684752, 2024). "In our animal study, chronic chlorella intake did not induce cardiac hypertrophy or change the mRNA expression levels of ANP, ET-1, and ACE in rat hearts." (PMID 40871685, 2025).
dementia (83 papers, 2008 to 2026). Loss of intellectual abilities interfering with an individual's social and occupational functions. "A meta‐analysis illustrated that ARBs were more effective than ACE inhibitors in reducing the risk of cognitive impairment and dementia." (PMID 39828641, 2025). "Several studies suggest that the impact of antihypertensive medications on lowering the risk of dementia is associated with substances that help to maintain regular cerebral blood flow, such as CCBs, ACE inhibitors, and ARBs." (PMID 40818936, 2025). "Carriers of damaging ACE mutations exhibited a trend toward higher rates of dementia, hippocampal dysfunction, and frontal dysfunction compared to non-carriers, indicating a possible increased risk of these cognitive impairments." (PMID 41009662, 2025). "A retrospective cohort study found that ARBs were more effective than ACE inhibitors in reducing the risk of cognitive impairment and dementia in hypertensive patients." (PMID 39828641, 2025). "Scientists have also noticed additional beneficial effects of ACE inhibitors on dementia risk, and these inhibitors have since been tested in AD cohorts with mixed results." (PMID 39766777, 2024). "A recent network meta-analysis compared use of various AHM classes to each other and demonstrated that use of CCBs and ARBs was associated with a 12–17% reduced dementia risk compared with ACE inhibitors and beta blockers, but less so versus diuretics (7–11%)." (PMID 36394298, 2023). "Another study has indicated that the combination of statins and angiotensin-converting enzyme (ACE) inhibitors significantly lowered the risk of dementia with possible AD in a cohort of people with a history of TBI." (PMID 36046494, 2022). "Several studies have found that patients on ACE inhibitors that cross the blood-brain barrier (centrally acting) are at reduced risk of dementia and have improved cognitive ability." (PMID 33541420, 2021). "We have found that none of the analysed polymorphisms in the genes of renin-angiotensin system, i.e. rs699, rs4762 in AGT, rs5186 in AGTR1, rs5194, rs1403543 in AGTR2 or ACE I/D was associated with MCI or dementia in Parkinson’s disease." (PMID 34302265, 2021). "One study found that peripheral ACE inhibitors are associated with an increased risk of AD, while others indicated that peripheral ACE inhibitors reduce dementia risk." (PMID 23948883, 2013). "However, their role in dementia is complex and varies with specific ACE gene variants, which have been associated with neurodegenerative processes." (PMID 40699836, 2025). "In a previous report of ACE inhibitors and hallucination, it is thought that older patients, particularly those with a history of either dementia or mild cognitive impairment, may be at higher risk for hallucination." (PMID 34155323, 2021). "One of them reported a two-fold higher risk of dementia in ACE II homozygotes compared to combined ID and DD genotypes (OR 2.17; 95% CI 1.22–3.85; p = 0.008); moreover, II carriers were more likely to develop dementia under the age of 70 (OR 4.35; 95% CI 1.37–13.86; p = 0.013)." (PMID 34302265, 2021). "Of the genes/proteins associated with dementia, six are consistent with the results obtained from VOSviewer: APP, MAPT, APOE, ACE, IL6, and CRP." (PMID 40699836, 2025). "The ACE, REN, APOE, CRP, and IL6 proteins obtained through this bioinformatic approach appear to be associated with both HF and dementia." (PMID 40699836, 2025). "The renin-angiotensin-aldosterone system (RAAS) has been shown to be dysregulated in dementia, with elevated levels of angiotensin-converting enzyme (ACE), angiotensin (Ang) II, and Ang II type 1 receptors (AT1Rs)." (PMID 40475476, 2025). "ACE inhibitors (ACEi) or blockers of Angiotensin II receptors (ARB) have been shown to delay the cognitive decline and reduce the risk of dementia [reviewed in]." (PMID 36756193, 2023).
dementia (continued). "The recommended total ACE-III cut-offs for differentiating early-onset dementia patients from healthy controls are 82 and 88 for research and screening, respectively." (PMID 34566550, 2022). "When compared with ACE inhibitors or other cardiovascular drugs, the superior effects of ARBs on the incidence and progression of dementia and AD were also reported in earlier studies." (PMID 36051740, 2022). "In the present study, in the group of patients receiving ACE inhibitor, the average age was 78.4 years and 39% had dementia, while in the group of patients receiving ARB, the average age was 80.7 years and 61% had dementia." (PMID 34155323, 2021). "The aim of the presented research was to establish the impact of several polymorphisms in RAS—in the genes of angiotensinogen, ACE, AT1R, and AT2R—on the risk of mild cognitive impairment (MCI) or dementia in PD." (PMID 34302265, 2021). "Recently, studies have reported a significant reduction in the incidence of AD and dementia among patients taking angiotensin converting enzyme inhibitors (ACE-Is) and angiotensin receptor blockers (ARBs)." (PMID 33060184, 2020). "A combination consisting only of ACE inhibitor and diuretic reduced the occurrence of dementia by 31%." (PMID 27557144, 2016). "The mechanism of interaction of ApoE2 or ApoE3 and ACE inhibitors on delaying the dementia of AD is unclear." (PMID 23948883, 2013). "Clinical studies also suggested that ACE is involved in cognitive impairment in AD patients because ACE inhibitors delayed onset of dementia and significantly decreased the ACE activity in CSF." (PMID 23008812, 2012). "Although previous studies reported beneficial effects of ACE inhibition in dementia using several models, its involvement in colchicine-induced oxidative stress, impaired cholinergic function and memory has not been investigated." (PMID 23008812, 2012). "Perindopril dose dependently ameliorated colchicine-induced dementia in mice implicating central ACE in memory function." (PMID 23008812, 2012). "Since most of the identified proteins are not present in both diseases, we performed two independent PPI analyses: the first using the proteins associated with HF (NPPB, REN, ADIPOQ, VWF, ACE, IL6, and CRP) and the second using the proteins involved in dementia (CRP, APP, MAPT, APOE, ACE, and IL6)." (PMID 40699836, 2025). "We found that IL6, REN, CRP, and ACE play a role in dementia (purple spheres)." (PMID 40699836, 2025). "Other meta-analyses of observational studies have found ARBs but not ACE inhibitors led to significant reduction in risk of dementia." (PMID 40830462, 2025). "Additionally, the brain RAAS is dysregulated in dementias such as AD, with previous studies in humans and mouse models of dementia showing elevated levels of ACE, Ang II, and AT1Rs19–21." (PMID 40475476, 2025). "Recently, several studies have reported a significant reduction in the incidence and progression of dementia among some patients receiving antihypertensive medications such as angiotensin-converting enzyme inhibitors (ACE-Is) and angiotensin receptor blockers (ARBs)." (PMID 37113150, 2023). "Local RAAS blockade in the CNS by BBB-penetrating ACE inhibitors or ARBs, especially in the hippocampus, may promote additional benefits in preventing cognitive impairment and dementia." (PMID 36051740, 2022). "Examples include dry cough associated with angiotensin-converting enzyme (ACE) inhibitors, which may be managed by antitussive medication, and urinary incontinence associated with cholinesterase inhibitor use for dementia, which may be managed with oxybutynin." (PMID 30596002, 2018). "In this context, the suggested repurposing of ACE inhibitors for clinical conditions related to AD and other types of dementia could be a potential option, which deserves further study." (PMID 26697495, 2015).